EPO (erythropoietin)
Diseases named in the same sentence as EPO in open-access papers (continued):
Sharing a sentence is not in itself a finding about the gene and the disease.
systemic lupus erythematosus (11 papers, 2018 to 2025). An autoimmune multi-organ disease typically associated with vasculopathy and autoantibody production. "Our data in a murine model of lupus document that endogenous EPO reduces T- and B-cell activation and autoantibody production, supporting the conclusion that EPO physiologically acts as a counterregulatory mechanism to control immune homeostasis." (PMID 37520571, 2023). "However, decreases in the levels of EPO and the EPO receptor have been observed in a pristane-induced murine lupus model." (PMID 39611168, 2024). "Furthermore, in pristane-induced lupus-like murine model, EPO therapy increased phagocytosis of apoptotic cells by macrophages and correspondingly decreased accumulation of dying cells." (PMID 33796104, 2021). "The erythropoietin signaling pathway is significantly upregulated in CM-positive human and mouse plasma, whereas HMGB1, IL-17, and systemic lupus erythematosus in B-cell signaling pathways were significantly downregulated in CM-positive plasma of both species." (PMID 35073748, 2022). "As demonstrated by these studies, EPO treatment reduced disease severity in both pristane-induced and spontaneous MLR/lpr lupus models." (PMID 33796104, 2021). "The anti-THPO antibody was reported to be found in patients with amegakaryocytic thrombocytopenic purpura, idiopathic thrombocytopenia purpura (ITP), systemic lupus erythematosus (SLE), in those treated with rhTHPO and recombinant human erythropoietin." (PMID 32260359, 2020). "We generated mice in which we could downregulate EPO production using a doxycycline (DOX)-inducible, EPO-specific silencing RNA (shEPOrtTAPOS), and we crossed them with B6.MRL-Faslpr/J mice that develop spontaneous lupus." (PMID 37520571, 2023).
cerebral malaria (10 papers, 2008 to 2024). A sequestration of Plasmodium falciparum in the brain, which can cause coma and/or seizures. "In a murine model of acute encephalopathy due to cerebral malaria, EPO was associated with a dose dependent improvement in survival, together with a significantly reduced number of apoptotic cells." (PMID 33796104, 2021). "In studies of mice with cerebral malaria, EPO treatment significantly inhibited DCs differentiation and reduced expression of costimulatory markers CD80 and CD86, and TLRs." (PMID 33796104, 2021). "Initially RDW was low in all the three categories, severe malarial anaemia (SA), cerebral malaria (CM), and uncomplicated malaria (UM), in spite of markedly increased concentrations of erythropoietin (EPO)." (PMID 27034825, 2016). "It has been successful in experimental murine cerebral malaria, and a recent human study showed that African children with high levels of erythropoietin were protected against neurological sequelae of cerebral malaria." (PMID 22287973, 2012). "Furthermore, induction of reticulocytosis by administration of erythropoietin is also protective in the P. berghei ANKA model of cerebral malaria, although direct anti-inflammatory and neuroprotective actions of erythropoietin may be involved as well." (PMID 29506544, 2018).
chronic kidney failure (10 papers, 2014 to 2025). "This alteration may arise from a decrease in erythropoiesis caused by intense bone marrow parasitism or from reduced erythropoietin production due to chronic kidney failure as a result of the disease." (PMID 37888600, 2023). "In situ bioproduction of recombinant erythropoietin in patients with chronic kidney failure, delivery of monoclonal antibodies to treat chronic immune diseases and enzyme replacement therapy are just a few of the possibilities." (PMID 39953326, 2025). "This meta-analysis was associated with the results of two clinical trials that evaluated the risk of cardiovascular diseases and benefits for the quality of life of patients with chronic kidney failure receiving EPO, the CHOIR and CREATE study." (PMID 38672425, 2024). "To evaluate the potential of cf-mRNA to monitor the activity of specific BM lineages after stimulation with growth factors, we obtained plasma from nine patients with varying degrees of chronic kidney failure on chronic maintenance erythropoietin (EPO) therapy." (PMID 31964864, 2020). "As impressive as it was for the efficacy of recombinant EPO to reduce the transfusion needs of patients with chronic kidney failure, the size of this patient population is not sufficiently great to justify the enormous commercial expansion of the drug." (PMID 38672425, 2024). "The product of the haemoglobin value multiplied by the EPO value in the peripheral blood of clinical diabetic kidney disease (DKD) patients exhibits a good correlation with DKD stage and can predict the chance of chronic kidney failure in the future." (PMID 34878225, 2022). "Disease pathway analysis showed IL6, EPO, ADIPOQ and CCR2 to be involved in chronic kidney failure." (PMID 25280384, 2014).
clear cell renal cell carcinoma (10 papers, 2011 to 2025). "Research suggests that clear cell renal cell carcinoma (CCRCC) originates from the renal erythropoietin-producing cell (EPC), which shows markers consistent with a neuroendocrine origin." (PMID 39429475, 2024). "Many studies have confirmed the overexpression of erythropoietin and its receptor in clear cell renal carcinoma." (PMID 30862152, 2019). "Suggesting therefore co-regulation of EPO and the spliced transcript hEPOΔ3 in diseased condition, we further studied expression profiles in a panel of clear cell renal cell carcinoma (ccRCC) samples and adjacent normal renal tissue." (PMID 28623280, 2017). "Clear-cell renal cell carcinoma (ccRCC) is associated with the mutated von Hippel–Lindau (VHL) gene leading to the activation of hypoxia-inducible factor 1A (HIF1A) and subsequent overexpression of erythropoietin (EPO)." (PMID 40332447, 2025). "The detection of the erythropoietin cell as the possible cell of origin of clear-cell renal cancer may be related to the role of HIF in renal carcinogenesis, and may hopefully result in new treatment options for this cancer." (PMID 34202596, 2021). "Furthermore, we have previously focused on the clinical similarities between clear cell renal cancer and NETs and have shown that virtually all clear cell renal cancers express erythropoietin." (PMID 32796591, 2020). "For instance, we have shown that the most prevalent type of kidney cancer, clear cell renal cell cancer (CCRCC), most likely originates from EPO cells." (PMID 38660133, 2024).
hyperphosphatemia (10 papers, 2013 to 2024). Abnormally high level of phosphate in the blood. "It has been reported that patients undergoing maintenance HD may develop hyperphosphatemia, which may be associated with increased protein intake, erythropoietin (EPO) therapy, intake of vitamin D, reduced physical activity, and so on." (PMID 24454542, 2013). "In addition, the increase of serum alkaline phosphatase and hyperphosphataemia may also play a role in chronic renal disease-associated anemia and EPO hypo-responsiveness and reduction in erythropoietin hormone (Epo) expression." (PMID 35576029, 2022). "The pre-existing pharmacological therapy is often integrated with specific medicines, such as anti-anaemic (iron and erythropoietin), treatments for hyperkalaemia and hyperphosphatemia, and anti-parathyroid agents, particularly paricalcitol." (PMID 38493085, 2024). "Hyperphosphatemia in BKO mice increased serum erythropoietin, FGF23, and PTH levels, nominating these factors as candidate mediators of bone loss in thalassemic mice with CKD during phosphate retention." (PMID 35622784, 2022). "These could be translated clinically into better control of hyperphosphatemia, a better erythropoietin response, and superior survival related to lower cardiovascular risk." (PMID 38276101, 2024). "Experimental data showed that treatment with EPO and HIF-PH inhibitors in anemic mice with CKD reduced iFGF23 levels by more than 70% without causing hyperphosphatemia, improved iron utilization, and restored the balance of genes responsible for 1,25 vitamin D production." (PMID 36831276, 2023).
infarction (10 papers, 2011 to 2025). A localised pathological necrosis of tissue resulting from obstruction of the blood supply usually by a thrombus, an embolus, or vascular torsion. "The ERI, an indicator used to evaluate EPO treatment responsiveness, can predict the occurrence of brain hemorrhage and infarction and all-cause death in MHD patients." (PMID 41244199, 2025). "Previous studies have shown that exogenous administration of EPO as well as increased endogenous serum EPO improves MI pathobiology by reducing the infarction size as well as improving cardiac function in a time dependent manner." (PMID 30719216, 2019). "In our study, epicardial EPO delivery resulted in superior left ventricular performance, reduced infarction size and attenuated cardiac remodeling after acute MI." (PMID 29752300, 2018). "In our study, focal analyses in intramyocardial cardiac MSC clusters documented activation of the EPO-R downstream signal mediator AKT in all EPO therapy groups in the peri-infarction area 24 h after MI." (PMID 29752300, 2018). "PEG with/out iPSC-CMs and EPO; iPSC-CMs in saline; or saline alone was injected into infarcted hearts shortly after infarction." (PMID 28988988, 2017). "One such agent, erythropoietin (EPO), has already been successful in the clinic for reduction of cell death and remodeling post MI and has shown benefits in experimental infarction when delivered using a gelatin cardiac patch." (PMID 28988988, 2017). "Eight studies found both a significant improvement in delayed cerebral ischemia/vasospasm/infarction and outcome including studies of nimodipine, nicardipine implants in the basal cistern, edavarone, pravastatin, fasudil, and erythropoietin." (PMID 23533956, 2013). "High doses of EPO, which are needed to achieve higher target hemoglobin levels, may be associated with an increased risk of brain hemorrhage, infarction and other events in MHD patients without any associated significant improvement in quality of life." (PMID 41244199, 2025). "In conclusion, epicardial EPO delivery induced early intracardiac regenerative key mechanisms, which could be relevant for improved early MI healing, angiogenesis and enhanced late remodeling, capillary density, infarction size and cardiac performance." (PMID 29752300, 2018). "Ultimately, the therapeutic value of EPO in clinical studies in the study population in terms of changes in mortality, arrhythmias’ incidence, thromboembolic events, MACE, LVEF, inflammatory biomarkers, and infarction size have also been discussed." (PMID 35812547, 2022). "Contrary to preclinical studies, EPO administration did not significantly have notable effects on mortality, major adverse cardiovascular events, or infarction size reduction." (PMID 35812547, 2022). "Treatment with MK-X efficiently decreased the infarction area, while EPO showed no significant protective effect." (PMID 28817120, 2017). "In contrast, EPO administration in MI did not significantly have beneficial effects in reducing mortality, MACE, infarction size, or amelioration in LVEF, as reported herein, differing from animal studies." (PMID 35812547, 2022). "Past studies have demonstrated nontherapeutic effects of upregulating erythropoietin (EPO), another HIF-1 alpha gene target, in the hippocampus and cerebral cortex, including BBB permeability prevention, brain edema reduction, decreased infarction volume, and post-HBOT neurobehavioral improvement." (PMID 32899709, 2020).
metabolic disorders (10 papers, 2015 to 2025). "Intestinal damage caused by EPO allows significant PS penetration, impacting gut microbiota and exacerbating oxidative stress and metabolic disorders." (PMID 39651483, 2024). "This could also explain why EPO levels decrease and are maintained within that range after a weight-loss therapy that is capable of improving metabolic disorders and inflammation, such as VLCKD." (PMID 38696124, 2024). "Chronic inflammation, often seen in metabolic disorders, can interfere with EPO signaling." (PMID 39518373, 2024). "The mechanism may be that they may exert cardiorenal protective effects and reduce the risk of metabolic diseases through the potential off-target effects of sodium proton exchange pumps, SGLT1, ketone bodies, and erythropoietin." (PMID 39767639, 2024).
optic neuritis (10 papers, 2016 to 2026). Optic neuritis is inflammation of the optic nerve, the nerve that carries the visual signal from the eye to the brain.The conditionmay cause sudden, reduced vision in the affected eye(s). "Among the included studies in our meta-analysis, we evaluated five novel agents for treating acute optic neuritis, namely memantine, EPO, INF-beta, phenytoin, and clemastine." (PMID 35052875, 2022). "One study on experimental optic neuritis model suggested that both neuronal and axonal protection, in functional and structural aspects, are most effective when combined erythropoietin and methylprednisolone treatment regimen was commenced." (PMID 31660109, 2019). "Systemic intravenous administration of EPO in optic neuritis, methanol optic neuropathy, and traumatic optic neuropathy was not fully investigated, although some pilot studies reported good anatomical and functional results, while others did not." (PMID 30647957, 2018). "In a phase II pilot trial in isolated optic neuritis, we have shown that treatment with erythropoietin in addition to methylprednisolone pulse therapy exerts protective effects on the retinal nerve fibre layer (RNFL) and the optic nerve (ON)." (PMID 27706045, 2016). "In order to further investigate our observations, which are limited by the comparably small group size, we have currently started a large phase III trial on erythropoietin in optic neuritis (ClinicalTrials.gov, NCT01962571)." (PMID 27706045, 2016). "Changes in cerebral lesion load by magnetic resonance imaging (MRI) in patients from a double-blind, placebo-controlled, phase II study on erythropoietin in clinically isolated optic neuritis (ClinicalTrials.gov, NCT00355095) were analyzed." (PMID 27706045, 2016). "Future studies into this matter could classify the severity of optic neuritis, administer EPO more closely to disease onset and extend the treatment duration to see the therapeutic effects of EPO." (PMID 35806148, 2022). "In this review, we summarized the available pre-clinical studies of EPO in treating glaucomatous optic neuropathy, optic neuritis, non-arteritic anterior ischemic optic neuropathy and traumatic optic neuropathy." (PMID 35806148, 2022). "Encouraging results of EPO from basic research support the possibility of integrating its therapeutic effects in glaucomatous optic neuropathy, optic neuritis, non-arteritic anterior ischemic optic neuropathy (NAION), and traumatic optic neuropathy (TON)." (PMID 35806148, 2022). "Although effective in terms of retinal nerve fiber layer protection, erythropoietin treatment of acute isolated optic neuritis did not influence further evolution of MRI lesions in the brain when comparing absolute numbers." (PMID 27706045, 2016). "This is in line with results from testing erythropoietin in an animal model of optic neuritis where it did not exert any anti-inflammatory or immunosuppressive effects." (PMID 27706045, 2016). "In an experimental autoimmune encephalomyelitis (EAE) rat model, intraperitoneal injection of EPO (5000 U/kg) significantly increased the survivability and functionality of RGCs in rats afflicted with myelin oligodendrocyte glycoprotein (MOG)-induced optic neuritis." (PMID 35806148, 2022).
Optic neuropathy (10 papers, 2018 to 2025). "Research on EPO in various ophthalmological conditions, such as ischemic retinal diseases, protection of RGCs, and optic neuropathies, has revealed promising therapeutic potential." (PMID 41300907, 2025). "Intravenous methylprednisolone or erythropoietin applications are also being attempted for methanol induced optic neuropathy." (PMID 40343573, 2025). "A combination of erythropoietin and a high dose of methylprednisolone were useful for relieving the critical optic neuropathy and improved the optical neurological disorder following methanol toxicity." (PMID 37076901, 2023). "With the clinical impression of optic neuropathy, he was treated with corticosteroid pulse (1 g/day) and intravenous EPO injection (20,000 IU/day) for 3 days." (PMID 36873065, 2023). "Here, we present a case of optic neuropathy due to methanol toxicity, treated by combination of intravenous and intravitreal EPO in addition to corticosteroid, which showed a remarkable improvement in the visual outcome." (PMID 36873065, 2023). "Currently, intravenous erythropoietin (EPO) administration appears to be a promising treatment for methanol-induced optic neuropathy, especially when it is combined with a standard treatment." (PMID 35270784, 2022). "EPO plays a vital role from the time of eye development to the many protective actions in optic neuropathies." (PMID 35806148, 2022). "Here, we review the latest evidence in the literature of the therapeutic effect of EPO in glaucomatous optic neuropathy and RGC death induced by different injury models." (PMID 36555679, 2022). "We summarize the available studies in the literature on the use of erythropoietin in these optic neuropathies." (PMID 35806148, 2022). "Therefore, we summarize the available studies involving the neuroprotective effects of EPO in optic neuropathies and propose future strategies involving EPO in optic nerve repair and protection." (PMID 35806148, 2022). "Understanding the features of EPO might result in the development of beneficial optic neuropathy treatments, including new delivery systems and derivatives with prolonged drug action of tissue protection and without erythropoietic side effects." (PMID 35806148, 2022). "Incorporating these therapeutic approaches with a better-controlled regulation could potentially magnify the beneficial effect of EPO for optic neuropathies in the future." (PMID 35806148, 2022). "Intravitreal injection of EPO may be effective and safe in treatment of recent and old indirect traumatic optic neuropathy." (PMID 30647957, 2018). "Finally, erythropoietin has been studied in ischemic ocular neuropathies, such as NAION, due to its potential neuroprotective and anti-apoptotic effects that may mitigate ganglion-cell loss, in addition to its role in toxic optic neuropathies." (PMID 41300907, 2025).